CCT6A (chaperonin containing TCP1 subunit 6A)
Diseases named in the same sentence as CCT6A in open-access papers (continued):
Sharing a sentence is not in itself a finding about the gene and the disease.
pulmonary fibrosis (1 paper, 2024). Chronic progressive interstitial lung disorder characterized by the replacement of the lung tissue by connective tissue, leading to progressive dyspnea, respiratory failure, or right heart failure. "To explore the regulation of CCT6A in the pathogenesis of lung fibrosis in vivo, we subjected adeno-associated virus serotype 2/9 (AAV2/9), either pcAAV-CMV-Cct6a-Flag or pcAAV-CMV to C57BL/6N mice via intratracheal delivery, and then intratracheal BLM or saline to the mice a week later." (PMID 38760881, 2024). "While the results of CCT6A in mice show positive outcomes, it is important to consider that ACE2s play a central role in the pathogenesis of pulmonary fibrosis." (PMID 38760881, 2024). "To further address the role of CCT6A in pulmonary fibrosis, we detected the expression of CCT6A in the lungs of mice with experimental pulmonary fibrosis induced by BLM." (PMID 38760881, 2024). "CCT6A inhibits lipid synthesis by blocking the production of lactate in AEC2s and alleviates bleomycin-induced pulmonary fibrosis in mice." (PMID 38760881, 2024). "As a result, mice overexpressing Cct6a showed significant attenuation of BLM-induced pulmonary fibrosis, including decreased lactate levels in serum and decreased lipid accumulation in the lungs, further demonstrating the therapeutic potential of CCT6A as a possible clinical target." (PMID 38760881, 2024). "Taken together, we further discovered the regulatory mechanism of lactate in pulmonary fibrosis and demonstrated that targeting CCT6A may be a viable strategy for treating pulmonary fibrosis." (PMID 38760881, 2024). "More importantly, overexpression of CCT6A in mice significantly inhibits BLM-induced lung fibrosis." (PMID 38760881, 2024). "In addition, we illustrated a crucial regulation for CCT6A in lactate signaling and the progression of lung fibrosis." (PMID 38760881, 2024). "However, from another point of view, our results are sufficient to prove the inhibition of CCT6A on glycolysis, which is a potential target for the treatment of pulmonary fibrosis." (PMID 38760881, 2024). "Following the observation that CCT6A could regulate lactate metabolism in cells cultured in vitro, we next investigated the regulation of CCT6A in experimental murine lung fibrosis." (PMID 38760881, 2024). "In conclusion, we propose that there is a pivotal regulatory role of CCT6A in lactate metabolism in pulmonary fibrosis, and strategies aimed at targeting these key molecules could represent potential therapeutic approaches for pulmonary fibrosis." (PMID 38760881, 2024). "Notably, compared with the saline group, BLM remarkably induced lung parenchymal fibrotic lesions in mice, while the administration of AAV2/9-Flag-Cct6a attenuated BLM-mediated lung fibrosis, as shown by hydroxyproline assays, H&E and Masson's trichrome staining." (PMID 38760881, 2024). "To further verify the inhibitory influence of overexpression of Cct6a on lung fibrosis in the mice injected BLM, we detected the expression levels of lung fibrosis related genes." (PMID 38760881, 2024).
testicular cancer (1 paper, 2021). A primary or metastatic malignant neoplasm that affects the testis. "In agreement, CCT6B high levels are specifically associated with testicular cancer, whereas high levels of CCT6A are associated with a broad range of cancers." (PMID 33846299, 2021).
tumor (29 papers, 2010 to 2025). "CCT6A expression in GC tumor tissues was associated with resistance to CGP60474 and SB52334, and sensitivity to camptothecin, TGX221, talazopanib, etoposide, gemcitabine, HG511301, TW37, vinorelbine, and gefitinib." (PMID 36010886, 2022). "This study also sought to clarify the association between tumor immune cell infiltrates and CCT6A expression in COAD." (PMID 34017352, 2021). "Research has also shown that CCT6A plays a tumour‐promoting role in a variety of tumours, but the specific underlying mechanism remains unknown." (PMID 39556022, 2024). "When interpreted as a whole, CCT6A may possess a role in polarization of tumor-associated macrophages (TAM)." (PMID 34017352, 2021). "K-M curves showed that tumor CCT6A high expression was associated with reduced OS (P < 0.001, χ2 = 28.058): the median OS was 42.0 (95%CI 33.2–50.8) months in CCT6A high expression patients and was 69.0 (95%CI 57.5–80.5) months in CCT6A low expression group." (PMID 32631353, 2020). "Furthermore, CCT6A is associated with T cell reduction in cytotoxicity, immune function loss, and reduced T cell cytotoxicity during exhaustion with prolonged exposure to tumor antigens." (PMID 34434188, 2021). "Through intratumoral injection model and multi-Omics analyses, we identified CCT6A as a novel tumor-derived exosomal protein, bridging TAMs M2 polarization and PDAC prognosis." (PMID 40374617, 2025). "In a co-culture system of CAFs and cancer cells, it is discovered that CCT6A is transferred from CAFs to tumor cells mainly via exosomal transport, thereby enhancing stemness, chemoresistance, and glycolysis." (PMID 40801472, 2025). "CCT3 promotes tumor proliferation, Sorafenib resistance, and ferroptosis sensitivity, while CCT6A regulates the G1‐to‐S phase transition, contributing to cell cycle dysregulation and tumor progression." (PMID 41312091, 2025). "In vivo, the xenograft model demonstrated that downregulation of CCT6A significantly inhibited tumor growth and negated the influence of TRIM38 knockdown on tumor progression." (PMID 40047371, 2025). "Pathological staining revealed that CCT6A expression was positively correlated with histological differentiation and tumor stage." (PMID 40374617, 2025). "In summary, the presented data showed that CCT6A was highly expressed in numerous tumor tissues and was closely related to the prognosis of various tumors." (PMID 39440061, 2024). "Compared with the adjacent normal tissues, the protein levels of CCT6A were higher in the tumor tissues of all tested cases." (PMID 39440061, 2024). "Another limitation is that the effect of CCT6A on the tumour microenvironment in a mechanistic study is still at the phenotypic level." (PMID 39556022, 2024). "As for the CRC, bioinformatics analysis and experimental validation indicated that CCT6A levels were higher in the tumor group than that in the normal group." (PMID 39440061, 2024). "To address these problems, we will recruit more eligible patients and further explore the effect of CCT6A on the tumour microenvironment." (PMID 39556022, 2024). "Validation through in vivo drug administration experiments has highlighted the substantial reduction in CCT6A‐driven tumour growth achieved through the synergistic application of Ipatasertib and anti‐PD1 therapy." (PMID 39556022, 2024). "Although CCT6A as a major regulation factor in tumor development, the detailed regulatory mechanism is still lacking." (PMID 38760881, 2024). "Meanwhile, the GEPIA database analysis also verified that CCT6A is highly expressed in multiple tumor tissues, in which COAD and READ included." (PMID 39440061, 2024). "Meanwhile, the CRC tissue microarray and CRC patients' tissues verified that CCT6A levels were higher in the tumor tissues than in the adjacent normal tissues." (PMID 39440061, 2024). "Due to the essential role of CCT in tumor growth, we further evaluated the effect of CCT6A knockdown on OS cell apoptosis." (PMID 36584147, 2022).
tumor (continued). "CCT6A was differentially expressed in subgroup analyses according to tumor grade, disease stage, histological subtypes, and age, but not gender." (PMID 34017352, 2021). "We found that CCT6A levels correlated negatively with levels of infiltrating B cells, CD4+T cells, neutrophils, and dendritic cells but positively associated with tumor purity, suggesting a potentially immune-suppressed role of CCT6A." (PMID 34017352, 2021). "Lower CCT6A expression was associated with higher infiltrating B cells, CD4+ T cells, neutrophils, and dendritic cells, but positively correlated with tumor purity." (PMID 34017352, 2021). "To solve this problem, we retrospectively screened 381 NSCLC patients and investigated the CCT6A expression in tumor tissue and adjacent tissue." (PMID 32631353, 2020). "Immunohistochemistry staining and semi-quantitative scoring were used to evaluate CCT6A expression in tumor and adjacent tissues." (PMID 32631353, 2020). "Our study found that tumor CCT6A high expression was an independent predictive factor for shorter DFS and OS in NSCLC patients." (PMID 32631353, 2020). "Cox’s regression analysis disclosed that tumor CCT6A high expression independently predicted worse DFS (P < 0.001) (hazard ratio (HR) 1.659 (95% confidence interval (CI) 1.318–2.089)), and OS (P < 0.001) (HR 1.779 (95%CI 1.378–2.298))." (PMID 32631353, 2020). "Kaplan–Meier curves displayed that tumor CCT6A high expression was negatively correlated with DFS and OS (all P < 0.001)." (PMID 32631353, 2020). "CCT6A was significantly higher expressed in tumor tissues compared with the paired normal tissues." (PMID 39440061, 2024). "Moreover, CCT6A knockdown was observed to decrease the Ki-67 index, indicating a reduction in tumor cell proliferation." (PMID 38750462, 2024). "Research has established the tumour‐promoting role of CCT6A in a variety of tumours." (PMID 39556022, 2024). "Furthermore, we also explored the association of tumor CCT6A expression with clinicopathological features and observed that tumor CCT6A high expression was correlated with LYN metastasis, raised TNM stage, and abnormal CEA in NSCLC patients." (PMID 32631353, 2020). "CCT6A expression was elevated in tumor tissue (CCT6A high 47.5% vs. low 52.5%) compared with adjacent tissue (CCT6A high 30.4% vs. low 69.6%) (P < 0.001), and ROC curve displayed that CCT6A could distinguish tumor tissue from adjacent tissue." (PMID 32631353, 2020). "Some recent studies uncover the role of CCT6A in tumor pathology." (PMID 32631353, 2020). "Hence, our study enrolled 381 NSCLC patients to detect the expression of CCT6A in tumor and adjacent tissues and investigated the correlation of tumor CCT6A expression with clinicopathological features and survival profiles in these NSCLC patients." (PMID 32631353, 2020). "Also, we observed that CCT6A expression was elevated in tumor tissue compared with adjacent tissue (P < 0.001)." (PMID 32631353, 2020). "Kaplan–Meier (K-M) curves showed that tumor CCT6A high expression was associated with decreased DFS (P < 0.001, χ2 = 26.823): the median DFS was 30.0 (95%CI 24.4–35.5) months in CCT6A high expression patients and was 48.0 (95%CI 42.5–53.5) months in CCT6A low expression patients." (PMID 32631353, 2020). "In addition, the IHC images of four types of tumors (HNSC, KIRP, LIHC, LUAD) were downloaded from the HPA database, and these representative images showed that the staining intensity of CCT6A in tumor tissues was significantly higher than that in normal tissues." (PMID 39440061, 2024). "Interestingly, among these HSPs, overexpression of HSPA2 and DNAJC20 was associated with better prognosis (tumor suppressor-like activity), whereas high expression of other heat shock genes (HSP90AA1, CCT1, CCT2 and CCT6A) correlated with poor survival (oncogene-like activity)." (PMID 31101846, 2019). "The IHC results showed that ERO1A, CCT6A, and SHC1 were significantly overexpressed in tumor tissues compared to normal samples." (PMID 40953006, 2025).
tumor (continued). "To verify the relationship between tumoral CCT6A expression and TAM status, we collected tumor samples from 33 PDAC patients." (PMID 40374617, 2025). "According to GSE32863 sequencing data, increased expression of CCT3, CCT4, CCT5, CCT6A, CCT7, and CCT8 was observed in LUAD tumor tissues compared with paired normal tissues." (PMID 39259093, 2024). "The results showed that GPI, IL22RA1, CCT6A, and SPOCK1 expression in the tumor tissues (T) was markedly higher than in the control tissues (N) (n=40, P<0.05)." (PMID 35433415, 2022). "The results of GEPIA showed that the expression levels of CCT6A and FAP were increased in the tumor tissues of GC patients, and the expression levels of ZFP36 and TP53I3 were decreased in the tumor tissues of GC patients." (PMID 36010886, 2022). "Eight genes centromeric to SEPT14 (ZNF713, MRPS17, GBAS, PSPH, CCT6A, SUMF2, PHKG1 and CHCHD2) were amplified in tumour 4 only." (PMID 21170331, 2010). "Collectively, these findings suggest that exosomal CCT6A in PDAC may contribute to M2 macrophage polarization, thereby promoting tumor progression." (PMID 40374617, 2025). "The effect of CCT6A on LUAD’s tumorigenic potential was additionally assessed in vivo through the subcutaneous injection of A549 cells into BALB/c-nude mice, which showed that CCT6A knockdown significantly slowed tumor volume and weight growth." (PMID 38750462, 2024). "Notably, iCAFs marked by TPM2 were enriched in the initial differentiation phase while myCAFs characterized by BIRC3, CCT6A, HNRNPF, and ID1 were enriched in the terminal differentiation phase during tumor progression." (PMID 37968457, 2023). "In summary, our results indicated that subunits of TRiC displayed varying degrees of abnormal expressions, and CCT2, CCT3, CCT5, CCT6A, CCT7, and CCT8 were significantly upregulated in BCa patients and their upregulation was positively correlated with BCa tumor stage." (PMID 33815471, 2021). "In summary, CCT6A expression is upregulated in NSCLC tumor tissue compared with adjacent tissue; meanwhile, its high tumor expression correlates with LYN metastasis, increased TNM stage, abnormal CEA, and independently predicts poor DFS as well as OS in NSCLC patients." (PMID 32631353, 2020). "CCT6A exhibited the strongest negative correlation at T1, which decreased with tumour stage progression." (PMID 30578123, 2019). "Notably, both the tumor growth curve and final tumor weight measurements demonstrated that the anti-CD47 nanobody achieved a more effective therapeutic outcome in tumors with CCT6A knockdown, compared to the scramble control group." (PMID 40374617, 2025). "Data from the UALCAN database indicated that CCT4, CCT5, CCT6A, and CCT8 exhibited significantly higher promoter methylation in normal tissues than in tumor tissues, suggesting that low promoter methylation may be responsible for upregulating these CCTs in LUAD." (PMID 39259093, 2024). "Therefore, we proposed that the CCT6A gene may serve as a key target in LUAD by modulating pathways such as PI-3K/AKT/mTOR, thereby affecting immune cell infiltration in the tumor microenvironment (TME) and playing a critical role in NSCLC progression and drug resistance." (PMID 40953006, 2025). "Heat shock-activated HSF1 is mainly responsive to the expression of heat shock proteins, while activation of HSF1 in tumor tissues is predominantly responsible for controlling the expression of non-heat shock proteins, e.g. CKS2, LY6K, RBM23, CCT6A, CKS1B, ST13 and EIF4A2." (PMID 25199534, 2014).
cancer (28 papers, 2016 to 2025). A tumor composed of atypical neoplastic, often pleomorphic cells that invade other tissues. "In the current study, we showed that CCT6A is highly expressed in several cancers and associated with OS through bioinformatics analysis." (PMID 39440061, 2024). "Conversely, the high expression of other four HSPs (HSP90AA1, CCT1, CCT2, CCT6A) was associated with poor prognosis (survival Z-score > 0) for most types of cancer." (PMID 31101846, 2019). "Several CCT subunits, such as CCT2, CCT3, CCT4, CCT5, CCT6A, and CCT7, have been implicated in cancer progression." (PMID 40867231, 2025). "Utilizing a human CRC tissue microarray and patients' surgically resection tissues, we verified that CCT6A is highly expressed in the cancer tissues." (PMID 39440061, 2024). "The results showed that CCT6A expression levels were higher in the cancer biopsies compared with the matched normal tissues (Mean of differences (T - N): 1.660, SD of differences: 3.121, 95% CI: 0.7731 to 2.547)." (PMID 39440061, 2024). "Here, we explored the expression level of CCT6A from the perspective of pan-cancer and multi-omics, analyzed the immune value of CCT6A, and preliminary verified its role in regulating cell proliferation/migration in CRC cells." (PMID 39440061, 2024). "CCT6A is considered a key regulator of several cancers and a newly discovered clinical biomarker which is associated with survival and prognosis of patients." (PMID 38760881, 2024). "For instance, the expression patterns of CCT6A in cancers were inconsistent when comparing the results from different databases." (PMID 39440061, 2024). "In OSCC, the presence of molecules such as CCT6A (Chaperonin containing TCP1 subunit 6A) is involved in carcinoma pathogenesis and progression through interrelated pathways." (PMID 39337467, 2024). "We investigated the single nucleotide variations (SNVs) of HFRS genes in different cancers and observed that some genes (CCT6A, TF, KRT14, P4HA2, PGK1, SLC16A2, and STC2) were frequently mutated in COAD, STAD, UCEC, and SKCM." (PMID 36998462, 2023). "We found that the CCT6A gene was significantly higher in some other cancer tissues than normal tissues." (PMID 34017352, 2021). "Another group of chaperone genes, such as CCT6A, CCT4, TCP1, CCT5, PTGES3 and CCT7, were previously implicated in cancer cell proliferation and predicts poor prognosis in HCC36,37." (PMID 33431814, 2021). "Correlation between high expression of CCT6A and good survival was observed just for 7/26 cancer types including SKCM, OV, LUSC, DLBC, GBM, LAML and READ." (PMID 31101846, 2019). "Additionally, the TCP1 subunit 6 A (CCT6A), which contains chaperone proteins, promotes various malignant cancer behaviors, and CCT6A enhances malignant activities in ESCC by activating the TGF-β/Smad/c-Myc pathway." (PMID 40544380, 2025). "Furthermore, we intravenously injected engineered luciferase‐labeled 4T1 cells to assess the influence of TRIM21 and CCT6A on cancer metastasis." (PMID 39556022, 2024). "In addition to an increase in the levels of CCT subunits in cancer cells, we found CCT6A mRNA expression to be greater in OS cells than in normal human osteoblasts." (PMID 36584147, 2022). "Existing literature reports CCT6A to possess oncogenic features in a various human cancer." (PMID 34017352, 2021). "In brief, these studies imply that CCT6A may be involved in disease initiation and progression in patients with specific cancers." (PMID 32631353, 2020). "All these data reveal that CCT6A may be dysregulated and be associated with the clinicopathological features of NSCLC patients, while little information was known about CCT6A in cancer progression of NSCLC patients." (PMID 32631353, 2020). "In clinical practices, CCT6A has been shown to be dysregulated in cancer patients." (PMID 32631353, 2020). "In addition, some studies support the role of CCT6A as a biomarker for survival in prediction in cancer patients." (PMID 32631353, 2020).